STAT3 (signal transducer and activator of transcription 3)
Diseases named in the same sentence as STAT3 in open-access papers (continued):
Sharing a sentence is not in itself a finding about the gene and the disease.
breast cancer (continued). "The hyperactivation of IL-6 and IL-1-dependent STAT3 signaling is correlated with poor patient prognosis and occurs in most human cancers including breast cancer." (PMID 35053592, 2022). "Clinically, cytoplasmic staining of IL-6Rα is significantly correlated with tamoxifen resistance in ER+ breast cancer patients suggesting IL-6/JAK/STAT3 is an actionable therapeutic target to sensitize tumor cells to current SOC treatment." (PMID 35371975, 2022). "Another report showed ANXA2 binds to STAT3 and promotes epithelial to mesenchymal transition in breast cancer cells." (PMID 35646067, 2022). "In this regard, the constitutive activation of STAT3 has been shown to mediate growth, survival, and invasion of breast cancer cells." (PMID 35406562, 2022). "It is unclear why there are differences in the conclusions drawn on the prognostic value of STAT3 in breast cancer." (PMID 35053592, 2022). "Using computational screening, we identified a candidate therapeutic compound that disrupted the interaction of SOST with STAT3 to inhibit STAT3 phosphorylation and reduce breast cancer bone metastasis." (PMID 36581888, 2022). "Numerous recent reports have shown that BA effectively inhibits lung cancer, melanoma, and breast cancer cell growth by repressing JAK2/STAT3 pathway." (PMID 36567856, 2022). "Our results indicate that CAAs can regulate the migration and invasion of breast cancer cells via the LIF/Stat3 axis." (PMID 35280694, 2022). "STAT3 signaling is heavily involved in immune evasion and chemoresistance in breast cancer, and ongoing research in this field is leading to new advances in therapies for advanced, high-grade metastatic disease." (PMID 35053592, 2022). "Inhibition of STAT3 at its N-terminal domain has shown promising anticancer activity in breast cancer cells." (PMID 35646067, 2022). "In preclinical model, F. prausnitzii found to suppress the growth of breast cancer through the inhibition of IL-6/STAT3 pathway." (PMID 35167406, 2022). "Our results depict that activated macrophages derived IL-6 regulates CSC enrichment, tumor growth, metastasis and angiogenesis in breast cancer through STAT-3 pathway." (PMID 35300689, 2022). "For breast cancer, resistin is involved in epithelial-mesenchymal transition and stemness, which are critical to metastasis and tumorigenesis via NF-κB/STAT3 pathways." (PMID 35073877, 2022). "As targets of the STAT3 signaling pathway, c-myc gene amplifications confer tamoxifen resistance in ER + breast cancer." (PMID 35154350, 2022). "For example, CDDO-Me is a triterpenoid with anti-inflammatory properties and suppresses activated STAT3 protein expression, nuclear translocation, and STAT3 anti-apoptotic genes in ovarian and breast cancer in vitro." (PMID 35371975, 2022). "In this study, we showed that breast cancer cells can upregulate OPG in stromal fibroblasts in an IL-6/STAT3-dependent manner." (PMID 36359766, 2022). "Taken together, these findings demonstrate that TAM derived IL-6 enhances the CSC phenotype in breast cancer cells through STAT-3 pathway." (PMID 35300689, 2022). "The overexpression of CDYL2 induces EMT and CSC maintenance in MCF7 and MDA-MB-231 breast cancer cells by increasing the Ser536 phosphorylation of p65 and STAT3 activity by Tyr705 phosphorylation, implicating both the NF-kB and STAT3 signaling pathways." (PMID 35740522, 2022). "IL-6 activates an autocrine JAK1-STAT3 signaling loop that in turn increases STAT3 activation in HER2+ breast cancer cells." (PMID 36291900, 2022). "We further demonstrate the role of TAMs derived IL-6 in enrichment of CSCs and tumor progression through STAT-3 pathway in breast cancer using both in vitro and in vivo models." (PMID 35300689, 2022). "Another finding also supported the role of STAT3 activation as a marker of favorable outcome in ER-positive/HER2-positive breast cancer patients." (PMID 36231093, 2022).
breast cancer (continued). "Utilizing a structural-based computational screening approach, S3I-201 was identified to target the SH2 domain of STAT3 and suppress downstream signaling to induce breast cancer cell apoptosis and exhibit activity in vivo in a TNBC mouse model." (PMID 35371975, 2022). "Previous studies reported that overexpression of SOCS3 suppresses JAK2/STAT3-signaling activation thus inhibiting the JAK2/STAT3-mediated EMT in breast cancer." (PMID 35719940, 2022). "Adipose-induced EMT in breast cancer cells can be reversed by inhibition of the IL-6/STAT3 signaling axis, by using U.S. food and drug administration (FDA)-approved anthelmintic niclosamide." (PMID 35701840, 2022). "They showed that in a spontaneous breast cancer model, ablating leptin-driven STAT3 signaling in CD8+ T cells enhanced the antitumor effect by reducing fatty acid oxidation (FAO) and promoting glycolysis." (PMID 35270020, 2022). "In breast cancer in particular, there are several studies on STAT3 and/or p-STAT3 expression and its function in human breast cancer specimens, each of which had different results." (PMID 35314590, 2022). "We also reported that carnosol inhibits breast cancer cell migration, invasion, and in ovo tumor growth, as well as targets STAT3, PCAF, and p300 to proteasome degradation." (PMID 35712465, 2022). "Then, adipocyte-secreted leptin promoted PAI-1-mediated breast cancer metastasis via activating the STAT3/miR-34a pathway in vivo." (PMID 35701840, 2022). "Studies on resistance of breast tumor stem cells (BCSCs) to chemotherapy have found that JAK/STAT3 signaling systems help breast cancer cells maintain their stem cell status, and resistance to chemotherapy by promoting fatty acid oxidation." (PMID 36591293, 2022). "The IL-6 signal transduction pathway including IL-6, IL-6R, sIL-6R, gp130, JAK, and STAT3 has been suggested as promising therapeutic targets for breast cancer." (PMID 35924148, 2022). "NOTCH4, on the other hand, enhances the STAT3 pathway and can be effective in amplifying breast cancer cells and reducing the effect of Tamoxifen." (PMID 35928368, 2022). "OSM-activated STAT3 cooperates with TGF-β to induce mesenchymal stem cells’ properties in breast cancer and in pancreatic cancer." (PMID 36077744, 2022). "Intriguingly, it was reported that GPX8/IL6/STAT3 axis was important for maintaining aggressive phenotype in breast cancer." (PMID 35978854, 2022). "Gene set enrichment analysis (GSEA) of public breast cancer patient databases showed that PD-L1 expression was also highly correlated with IL-6/JAK/STAT3 signaling." (PMID 35927628, 2022). "Here, we directly compared the activities of Chol-siRNA polyplexes and Chol-DsiRNA polyplexes in primary murine 4T1 breast tumors against STAT3, a therapeutically relevant target gene that is overexpressed in many solid tumors, including breast cancer." (PMID 35076584, 2022). "In this review, we examine evidence from pre-clinical studies that correlate enhanced IL-6 and IL-11 mediated gp130/STAT3 signaling to the progression of breast cancer." (PMID 35053592, 2022). "STAT3 and MMPs hold a key role in proliferation and evasion of the apoptotic pathway in metastatic breast cancers." (PMID 35216264, 2022). "A novel in-house prepared IL-6 pathway inhibitor namely 6a, which is capable of selectively inhibiting STAT3 activation following IL-6 stimulation in MDA-MB-231 breast cancer." (PMID 35924148, 2022). "Leptin secreted by adipocytes enhanced fatty acid oxidation by activating JAK/STAT3 signaling pathway in breast cancer stem cells." (PMID 35888767, 2022). "STAT3 is aberrantly active in breast cancer and promotes cancer growth through transcriptionally regulating target gene expression resulting in induction of G1 cell cycle progression, proliferation, anti-apoptosis, angiogenesis, and metastasis." (PMID 35371975, 2022).
breast cancer (continued). "To demonstrate the clinical relevance of PD-L1 expression and tumor acidosis, we determined the correlations among PD-L1, STAT3, and acidic microenvironment markers by analyzing breast cancer tissue." (PMID 35927628, 2022). "Specifically, leptin significantly increased PBX3 mRNA expression by enhancing the activity of the PBX3 promoter in a STAT3‐dependent manner in breast cancer (BC) cells." (PMID 35068042, 2022). "Nevertheless, the ERK/STAT3 cascade has become a key regulator of stimulating the M2-like polarization of macrophages and promoting tumor progression and metastasis in breast cancer TME." (PMID 35745800, 2022). "To identify potential therapeutics, we screened inhibitors of the interaction of SOST with STAT3 from a small chemical molecule library and tested the inhibitory effects of one inhibitor on breast cancer growth and bone metastasis in vitro and in vivo." (PMID 36581888, 2022). "This is corroborated by a meta-analysis and protein array data correlating nuclear phospho-STAT3 and STAT3 mRNA expression to more favorable outcomes for breast cancer patients." (PMID 35053592, 2022). "It is reported that miR-634 enhances the radiotherapy sensitivity of breast cancer cells by negatively regulating signal transducer and activator of transcription 3 (STAT3)." (PMID 36311195, 2022). "It is reported that ANXA2 enhances STAT3 activation and promotes proliferation and invasion of breast cancer cells." (PMID 35646067, 2022). "STAT3 expression level is significantly higher in TNBC than that in other breast cancers and normal tissues." (PMID 35414025, 2022). "Adipocyte-secreted leptin also enhanced the HER2 protein levels through a STAT3-mediated up-regulation of Hsp90 in breast cancer cells in vitro." (PMID 35701840, 2022). "Here, we present data showing that CAF-derived TIMP-1 activates STAT3 in breast cancer cells in cooperation with CD63 and integrin β1." (PMID 36291767, 2022). "Animal experiments have further confirmed that drugs that inhibit the JAK/STAT3 signaling system can greatly reduce the population of stem cells in breast cancer, and improve the efficiency of chemotherapy." (PMID 36591293, 2022). "Stat3 activation is a transient and tightly regulated process in normal tissues, but occurs constitutively in many human tumors, including breast cancers, most notably in triple-negative breast cancer (TNBC)." (PMID 36017196, 2022). "LIF is a pro-inflammatory cytokine secreted by CAAs, which promotes migration and invasion of breast cancer cells via the Stat3 signaling pathway." (PMID 35280694, 2022). "Treatment with apigenin significantly suppressed the aggressive type of breast cancer cells, the HER2-positive breast cancer type, by inhibiting the signal transducer and activator of transcription 3 (STAT3) signalling pathway." (PMID 36557789, 2022). "Compounds have also been repositioned for the treatment of breast cancer due to their anti-cancer activity through inhibition of STAT3, and are under preclinical investigation." (PMID 35371975, 2022). "The STAT3/ALDH1 axis has recently been proven to be a new pathway for increasing the stemness of breast cancer." (PMID 36060264, 2022). "Taken together, strategy targeting the IL-6/JAK/STAT3 signaling pathway, which has already been shown to be beneficial in certain cancers including breast cancer, has proven to be effective." (PMID 35924148, 2022). "Faecalibacterium prausnitzii inhibits the growth of breast cancer cells by inhibiting the IL-6/STAT3 pathway." (PMID 35889021, 2022). "Increased tyrosine phosphorylation of annexin A2 promotes proliferation, invasion, and STAT3 phosphorylation in breast cancer cells." (PMID 35646067, 2022). "The STAT3-G9a complex has also been reported to epigenetically silence the expression of miR-200c by depositing H3K9me2 marks on its promoter in MCF12A breast cancer cells." (PMID 35740522, 2022).
breast cancer (continued). "In the context of TNBC, the conditional deletion of STAT3 using the c-fms-iCre model increased mammary tumor incidence, an effect mediated by the induction of cyclooxygenase-2 (COX-2)." (PMID 35053592, 2022). "Clinical reports have indicated that the overexpression of STAT3 conduced to the progression of breast cancer." (PMID 35216134, 2022). "Treatments targeting the IL-6/JAK/STAT3 pathway have provided benefit for patients with breast cancer by directly inhibiting tumor cell growth and activating anti-tumor immunity." (PMID 35924148, 2022). "Previously, we and others have shown the prognostic and predictive roles of phospho-STAT3 (pSTAT3) in breast cancer, mainly in luminal tumors." (PMID 35327992, 2022). "PTPN6 dampens the oncogenic characteristics of breast cancer by dephosphorylating STAT3 and inactivating the Ras/extracellular signal-regulated kinase (Erk)/glycogen synthase kinase-3beta (GSK-3β) signaling pathway." (PMID 35957898, 2022). "We selected breast cancer SCP2 cells that are prone to bone metastasis to explore the molecular mechanisms and found that SOST promoted the proliferation of breast cancer cells by enhancing the STAT3/TGF-β/KRAS signaling." (PMID 36581888, 2022). "Accordingly, serum levels of IL-11, STAT3 and TGF-β were higher in patients with metastases to the bone compared with patients with only primary breast cancer, with the metastatic group showing associated poorer survival outcomes." (PMID 35053592, 2022). "Previous studies have consistently shown that SHP-1 agonists induce apoptosis via the SHP-1/p-STAT3 signaling axis in various cancer cells including hepatocellular carcinoma cells, breast cancer cells, and colorectal cancer cells." (PMID 35941532, 2022). "Next, we pretreated both U3A cells and SKBR3 human mammary carcinoma cells (both of which lack basal STAT3 phosphorylation) with folinic acid and pyrimethamine for 1 h and then stimulated with OSM to activate STAT3." (PMID 34953855, 2022). "It has been reported that in human breast carcinoma and lung adenocarcinoma cell lines, CuI inhibits STAT3 activation." (PMID 36355498, 2022). "Previous studies have reported that blocking Src tyrosine kinase activity can inhibit STAT3 signaling in melanoma and breast carcinoma cells." (PMID 36443287, 2022). "The constitutive activation of STAT3 is related to the occurrence of head and neck tumors, breast cancer, non-small-cell lung cancer, colorectal cancer, and hematological tumors." (PMID 34824210, 2021). "Immunohistochemical (IHC) analyses of human breast cancer samples reveal a high expression of p-STAT3 (Y705) and p-TrkA (Y490) in the tissue, supporting the co-activation of JAK2–STAT3 and TrkA pathways." (PMID 34066153, 2021). "We demonstrated that inhibition of STAT3 resulted in reduced PD-L1 expression in breast cancer cells." (PMID 33456560, 2021). "Concordantly, some studies have revealed that blocking of STAT3 in breast cancer animals significantly decreased the Tregs proportion in the TME especially the Foxp3+ Tregs." (PMID 33957948, 2021). "On the one hand, resveratrol, at low doses, has been demonstrated to inhibit lung metastasis in breast cancer by decreasing the generation and function of tumor-evoked regulatory B cells (tBreg) via the inhibition of the STAT3 pathway." (PMID 33572626, 2021). "In breast cancer, obesity-driven leptin/STAT3 signalling promoted FAO and reduced glycolysis in CD8+ T-effector cells, consequently leading to the inhibition of effector functions and facilitation of tumour growth." (PMID 34722305, 2021). "The S100A8/A9-mediated ROS suppression was reported to improve the CD4+ T cell accumulation in TME of breast cancer, which has been known to be regulated in STAT3-dependent mechanism in MDSCs." (PMID 33957948, 2021).
breast cancer (continued). "In breast cancer, incessant activation of STAT3 appears to be attributable to the upregulation of the pro-inflammatory cytokine IL-6 and S1PR1." (PMID 34820423, 2021). "MiR-495 targets STAT-3 to inhibit cell proliferation and migration and to induce apoptosis in breast cancer." (PMID 34575183, 2021). "The data presented here provide the first evidence that the transcriptional activation of WASF3 is synergistically regulated by SHOX2 and STAT3 through their assembly of a functional complex on the WASF3 promoter in breast cancer cells." (PMID 34465361, 2021). "The interaction between EZH2 and STAT3 as well as the STAT3 methylation by EZH2 was also detected in another breast cancer cell line MDA-MB-231 cells as well." (PMID 34335938, 2021). "Activated STAT3 directly binds these promoters, thus inducing their transcription and up-regulation, and this delays apoptosis and enriches a sub-population of breast cancer cells that have stem cell-like properties." (PMID 35126059, 2021). "For example, in these years, it was demonstrated that progestins were able to activate STAT3 in breast cancers by inducing phosphorylation of Y705 or S727." (PMID 34440160, 2021). "It was recently confirmed that STA-21 (ochrimycinone), a STAT3 inhibitor that was developed with the purpose of being a treatment for human breast cancer, has the possibility of treating psoriasis." (PMID 34445513, 2021). "Although direct evidence between IL-30 and the classical EMP markers remain elusive, IL-30 was shown to induce TNBC cell migration and the expression of a pro-oncogenic program to promote breast cancer growth and progression via STAT3." (PMID 34361105, 2021). "Activation of the STAT3 pathway is linked to both adipocyte-induced EMT and stemness in breast cancer cells." (PMID 34561446, 2021). "STAT3 activation has been previously associated with trastuzumab and trastuzumab–emtansine resistance in HER2-positive breast cancer." (PMID 34948097, 2021). "Stattic, a nonpeptidic small molecule has been shown to selectively inhibit the phosphorylation, dimerization, and nuclear translocation of STAT3, which consequently promotes the STAT3-dependent breast cancer cell death." (PMID 33957948, 2021). "In this study, we provide important mechanistic insights into the detrimental biological functions of opioids in breast cancer progression, as evidenced by their capacity to increase migration and metastasis through STAT3 activation and EMT reprograming." (PMID 33465556, 2021). "It was suggested that EGF (epidermal growth factor) secreted by TAMs interacts with EGF receptors on breast cancer cells to further activate the STAT3/Sox2 signaling pathway to induce the CSC stemness phenotype." (PMID 34178692, 2021). "For instance, Eucannabinolide (Euc) suppressed the STAT3 activation and DNA binding capacity, eventually leading to the inhibition of breast cancer cell viability, proliferation and metastasis." (PMID 33957948, 2021). "Taken together, these data suggest that TrkA-mediated phosphorylation and activation of STAT3 can induce STAT3 nuclear transport and the transcription of STAT3 target genes that promote breast cancer stem cells." (PMID 34066153, 2021). "For example, in the TME of breast cancer, STAT3 activation promotes the expression of fatty acid oxidation (FAO) in CD8+ T cells, which subsequently inhibits the cellular glycolysis and other functions." (PMID 33957948, 2021). "The top three phenotypes for the BRCA1 gene were ovarian cancer, breast cancer and cancer, and the top three phenotypes for the STAT3 were prostate cancer, retinoblastoma, and Buckley syndrome." (PMID 34315992, 2021).